MC4R (melanocortin 4 receptor)
Description:
G protein-coupled receptor that binds melanocyte-stimulating hormones (alpha- and beta-MSH) and corticotropin/ACTH, which are peptide products of the POMC precursor. Functions as a central component of the leptin-melanocortin pathway, which is essential for maintaining energy homeostasis. Upon activation, couples to G(s) protein, stimulating adenylate cyclase and the cAMP-dependent signaling pathway, which promotes anorexogenic signaling in the hypothalamus and contributes to a negative energy balance. Regulates food intake: activation by agonists suppresses appetite, whereas the antagonist Agouti-related protein/AGRP precludes agonist-induced signaling, thereby stimulating appetite. Modulates the firing activity of neurons in paraventricular nucleus (PVN) of the hypothalamus via alpha-MSH and AGRP regulation of inwardly rectifying potassium channel KCNJ13 closure, independently of G(s) signaling. In the PVN, also interacts with opsin 3/OPN3, which couples to G(i/o) proteins to inhibit MC4R-mediated cAMP signaling, thereby promoting food intake. In intestinal epithelial cells, contributes to inhibition of hepatic glucose production via nesfatin-1/NUCB2, leading to increased cAMP levels and glucagon-like peptide 1 (GLP-1) secretion. Interaction with MGRN1 displaces the G(s) protein, further decreasing MC4R signaling activity. Also activated by gamma-MSH, though with low potency.
Synonyms: BMIQ20
Tractability: Small molecule: a drug acting on it is in phase 2 or 3 trials; a structure with a bound ligand is known; a high-quality ligand is known; it belongs to a druggable protein family. Antibody: UniProt places it where antibodies can reach, with high confidence; its Gene Ontology location is reachable by antibodies, with high confidence; UniProt predicts a signal peptide or a membrane-spanning region. PROTAC: a small molecule that binds it is known. Other modalities: an approved drug acts on it.
Target class: Short peptide receptor (family A GPCR); Peptide receptor (family A GPCR); Melanocortin receptor; Membrane receptor; Family A G protein-coupled receptor
Chemical probes: CHEMBL1209788, CHEMBL264190, CHEMBL3601426, PD080887, PD081003, PD081119, PD081759, PD082602, PD083181, PD083446, PD083922, PD084498, PD084860, PD085099, PD085292, THIQ (high quality)
Safety:
Unwanted effects reported when the protein is acted on. In parentheses: how it was acted on, where the effect was seen, and who reports it.
weight gain (source: ClinPGx)
Gene: Protein-coding gene on chromosome 18 (60,371,062 to 60,372,775, reverse strand). Ensembl gene ENSG00000166603.
Subcellular location: Cell membrane; Cell projection, cilium membrane
Pathways (Reactome):
Signal Transduction: G alpha (s) signalling events; Peptide ligand-binding receptors
Developmental Biology: Transcriptional and post-translational regulation of MITF-M expression and activity
Gene Ontology:
Molecular function: corticotropin receptor activity; melanocyte-stimulating hormone receptor activity; neuropeptide binding; protein binding; ubiquitin protein ligase binding; melanocortin receptor activity; G protein-coupled receptor activity
Biological process: adenylate cyclase-activating G protein-coupled receptor signaling pathway; negative regulation of appetite; positive regulation of bone resorption; adenylate cyclase-modulating G protein-coupled receptor signaling pathway; feeding behavior; regulation of eating behavior; regulation of feeding behavior; response to melanocyte-stimulating hormone; G protein-coupled receptor signaling pathway; negative regulation of feeding behavior; neuropeptide signaling pathway
Cellular component: non-motile cilium membrane; plasma membrane; cytoplasm; membrane; ciliary membrane
Genetic constraint (gnomAD): Loss-of-function variants: 15 observed, 17.21 expected, observed/expected ratio (o/e) 0.87, 90% interval 0.58 to 1.34. The upper end of that interval is the gene's LOEUF score, 1.34, which puts it in group 5 of 6, group 1 being the genes least tolerant of losing a copy. Missense variants: 416 observed, 433.74 expected, observed/expected ratio (o/e) 0.96, 90% interval 0.88 to 1.04. Synonymous variants: 162 observed, 160.97 expected, observed/expected ratio (o/e) 1.01, 90% interval 0.88 to 1.15.
Homologues: Orthologues: chimpanzee MC4R (99% identical), macaque MC4R (99% identical), guinea pig MC4R (98% identical), rabbit MC4R (97% identical), pig MC4R (96% identical), dog MC4R (96% identical), mouse Mc4r (94% identical), tropical clawed frog MC4R (73% identical), zebrafish mc4r (68% identical). Paralogues in human: MC5R (61% identical), MC3R (55% identical), MC1R (45% identical), MC2R (42% identical), S1PR1 (24% identical), GPR12 (24% identical), LPAR1 (23% identical), S1PR3 (23% identical), CNR1 (22% identical), LPAR2 (22% identical), GPR6 (22% identical), S1PR2 (22% identical), and 6 more.
Diseases named in the same sentence as MC4R in open-access papers:
MC4R is named in the same sentence as 192 diseases in open-access papers, as found by Europe PMC text mining. Sharing a sentence is not in itself a finding about the gene and the disease. The quoted sentences say what the papers report.
Obesity (966 papers, 2006 to 2026). Accumulation of substantial excess body fat. "The clinical manifestation of monoallelic MC4R deficiency shows considerable variability in obesity severity." (PMID 41489710, 2026). "Panel sequencing of monogenic obesity genes was performed in the index patient whereas in the relatives targeted analysis of the familial MC4R variant was performed by Sanger sequencing." (PMID 41489710, 2026). "This case demonstrates the critical role of early genetic testing in children with severe, early-onset obesity, which led to the identification of the same MC4R variant in four family members across four generations." (PMID 41489710, 2026). "Monogenic obesity due to monoallelic MC4R variants can present with severe early-onset obesity yet often remains undiagnosed for generations." (PMID 41489710, 2026). "Expressed predominantly in the hypothalamus, MC4R is a key mediator of body weight regulation, and loss-of-function variants in this gene represent the most frequent cause of monogenic obesity." (PMID 41489710, 2026). "It has been widely used to assess numerous genes associated with obesity, such as MC4R, MC3R, neuropeptide Y, leptin and its receptor." (PMID 41596694, 2026). "Functional effects of five obesity-associated MRAP2 variants were analysed in HEK293 cells by co-expressing wild-type or variant MRAP2 with MC4R or GHSR." (PMID 41758604, 2026). "Melanocortin 4 receptor (MC4R) deficiency is the most common monogenic cause of obesity, yet remains underdiagnosed." (PMID 41489710, 2026). "Obesity is a multifactorial disorder, but more than 15 gene mutations can result in monogenic obesity in humans, such as MC4R." (PMID 41596694, 2026). "The MC4R variant rs17782313 is significantly associated with obesity under both the allele contrast model and the dominant model." (PMID 41596694, 2026). "While biallelic MC4R variants are exceedingly rare, pathogenic monoallelic MC4R variants are present in up to 5.8% of individuals with severe, early-onset obesity." (PMID 41489710, 2026). "Given the clinical suspicion of monogenic obesity, genetic panel testing of six genes related to monogenic obesity was conducted and identified a rare monoallelic (heterozygous) variant in the MC4R gene (c.913C > T; p.(Arg305Trp), ENST00000299766)." (PMID 41489710, 2026). "Leptin stimulates the POMC neuron, causing release of α-MSH, which acts on MC4R, increasing satiety and reducing obesity." (PMID 41002740, 2025). "The melanocortin-4 receptor gene (MC4R) has so far been associated with an increase in body mass index (BMI) and risk of obesity." (PMID 38879444, 2025). "Hyperphagia can also cause distress and negatively affect the families and caregivers of patients with MC4R pathway‐associated obesity." (PMID 40528426, 2025). "Setmelanotide (Imcivree®, Rhythm Pharmaceuticals, Inc., Boston, MA, USA) is a melanocortin-4 receptor (MC4R) agonist indicated only for the treatment of obesity caused by deficiency in MC4R signaling." (PMID 41471111, 2025). "Mutations in LEP, LEPR, POMC, and MC4R disrupt this regulatory loop, resulting in hyperphagia, reduced satiety, and early-onset obesity." (PMID 40281302, 2025). "The melanocortin-4 receptor gene (MC4R) is associated with a higher risk of obesity by the presence of the C allele in rs17782313, but the mechanisms are not clear." (PMID 38879444, 2025). "This review focuses on the unmet need for fit‐for‐purpose tools to assess and diagnose hyperphagia in patients with monogenic, syndromic, and acquired forms of obesity associated with MC4R pathway diseases that affect energy balance." (PMID 40528426, 2025). "The SNP analysis of the MC4R gene indicated that the rs17782313 polymorphism is correlated with obesity, particularly in conjunction with the LEP GG genotype." (PMID 41423640, 2025). "The MC4R gene mutation is the most frequent cause of monogenic obesity, and it shares several clinical aspects with forms of multifactorial obesity." (PMID 40428410, 2025).
Obesity (continued). "In summary, our studies demonstrate that human MRAP2 variants that are associated with obesity impair MC4R signaling by affecting multiple signaling pathways." (PMID 39807633, 2025). "Cumulatively, these studies in people from the GOOS and UK Biobank demonstrate that obesity due to MC4R deficiency is associated with reduced total cholesterol, LDL-cholesterol, TGs and hypertension, and relative protection from CVD." (PMID 41102563, 2025). "Genetic polymorphism in MC1R, MC2R, MC3R, and MC4R genes is associated with risk of melanoma, familial glucocorticoid deficiency, obesity, and type 2 diabetes mellitus, respectively." (PMID 41002740, 2025). "Such as the MC4RF51L in mice creates poor transport functionality MC4R/Gq/11α signaling that causes obesity and hyperphagia." (PMID 40024983, 2025). "In this study, it was aimed to determine the polymorphisms in MC4R gene in random bred cats and cats belonging to a registered breed in Turkey and to investigate their relationship with obesity." (PMID 40035963, 2025). "On the other hand, the MC4R (melanocortin-4 receptor) gene, which codes an important protein for appetite suppression, has variants that paradoxically increase obesity risk but have independent effects on depression." (PMID 41375608, 2025). "We have studied the largest available cohort of people with MC4R deficiency, providing insights into the genetic and clinical spectrum of this disorder, the most common monogenic form of obesity." (PMID 41102563, 2025). "Bardet-Biedl syndrome (BBS) is a rare genetic disease associated with disruptions in melanocortin-4 receptor pathway signaling that can contribute to increased risk for metabolic syndrome and obesity-related comorbidities." (PMID 39919037, 2025). "Mutations in the melanocortin 4 receptor (MC4R) gene, such as rs17782313 (T/C), are associated with monogenic forms of severe early-onset obesity and have been implicated in an increased risk of breast cancer." (PMID 41269404, 2025). "A lack of association with energy intake is difficult to understand given that it is well evidenced that the C allele of the MC4R rs17782313 polymorphism is associated with obesity, as proven by the latest meta-analyses found in the literature." (PMID 38879444, 2025). "Common and rare variants in MC4R have been implicated in obesity, metabolic syndrome, and type 2 diabetes." (PMID 40630117, 2025). "Research is underway to further validate these measures for use in clinical trials for BBS and other MC4R pathway-related diseases associated with obesity." (PMID 40847358, 2025). "Mutations in MC4R are the most common cause of monogenic obesity and can affect multiple signaling pathways including Gs-cAMP, Gq, ERK1/2, β-arrestin recruitment, internalization and cell surface expression." (PMID 39807633, 2025). "Third, although MC4R deficiency causes steatosis via hyperphagia and obesity, we found that aggregated ultra-rare variants in MC4R were negatively associated with predicted PDFF." (PMID 40065360, 2025). "MC4R is a principal regulator of satiety, as evidenced by the hyperphagia and obesity in MC4R-deficient models and the orexigenic effects of its antagonists." (PMID 41468751, 2025). "In humans, excessive sugar intake has been linked to obesity and metabolic syndrome, and MC4R mutations represent the most common monogenic cause of obesity." (PMID 40956393, 2025). "Clinical advancements include setmelanotide (IMCIVREETM, Rhythm Pharmaceuticals), an MC4R agonist approved for monogenic obesity disorders (POMC, LepR deficiencies)." (PMID 40278960, 2025). "Genetic variations in FTO, BDNF, and MC4R genes, related to increased risk of weight gain, have been reported to be linked to elevated BMI and obesity risk in large-scale genome-wide association studies." (PMID 40423790, 2025). "For example, mutations in MC4R are the primary reason for monogenic obesity and are recognized to disrupt satiety signals, resulting in hyperphagia and obesity that begins early." (PMID 40428329, 2025).
Obesity (continued). "MC4R mutations and genetic variants have been identified as the most common monogenic causes of severe early-onset obesity." (PMID 41002740, 2025). "The melanocortin 4 receptor (MC4R) gene plays a crucial role in energy balance, and pathogenic variants are associated with monogenic forms of obesity." (PMID 40428329, 2025). "Consistent with previous studies we showed that wild-type MRAP2 enhances MC4R coupling to Gs and increases cAMP signaling, and demonstrated that most obesity-associated MRAP2 variants impair cAMP signaling." (PMID 39807633, 2025). "We also consistently identified multiple association signals of high effect in MC4R, which is a well-established monogenic obesity gene, through our discovery analysis, internal conditional analysis, and rare variant aggregate analysis." (PMID 40216759, 2025). "BBS is a genetic obesity syndrome in which the MC4R pathway is implicated in the pathogenesis of hyperphagia and obesity." (PMID 40528426, 2025). "MC4R is the most common form of monogenic obesity, with variants found in around 5% of patients with obesity." (PMID 40636093, 2025). "One case report described the use of methylphenidate for 37 months as obesity treatment in a 3-year-old patient with heterozygous MC4R deficiency, which had resulted in a -11.2 kg/m2 decrease in BMI and improvement of hyperphagia." (PMID 39929239, 2025). "Recent GWAS identified rs17782313, located 188 kb downstream of MC4R, as one of the strongest BMI-associated variants, highlighting its central role in obesity susceptibility." (PMID 41302083, 2025). "In summary, our studies demonstrate that human MRAP2 variants associated with obesity impair multiple MC4R signaling pathways and that both Gs-cAMP and Gq-IP3 pathways should be assessed to determine variant pathogenicity." (PMID 39807633, 2025). "Mutations in the MC4R pathways are the most common single-gene disorders leading to human obesity with a prevalence of 1% to 6% in the obese population, and are especially common in severe childhood-onset obesity." (PMID 40232848, 2025). "Dysfunction of POMC neurons or the MC4R leads to severe obesity and associated metabolic comorbidities." (PMID 40541585, 2025). "Heterozygous loss-of-function (LoF) variants in MC4R represent the most common penetrant genetic form of obesity described to date." (PMID 41102563, 2025). "For example, loss-of-function (LOF) variants within the MC4R gene cause monogenic obesity; however, other missense variants in the same gene that are gain-of-function (GOF) are associated with protection against obesity." (PMID 40473624, 2025). "Key genes implicated in monogenic obesity include those involved in the leptin-melanocortin signaling pathway, such as MC4R, LEPR, PCSK1, and POMC, among others." (PMID 40281302, 2025). "Monogenic forms of obesity are estimated to account for 4% to 6% of severe obesity before age 6, with LEPR and MC4R genes being the most common etiologies.An estimated 5% to 6% of children and adults with obesity have a MC4R germline pathogenic." (PMID 40585884, 2025). "Inactivating mutations in MC4R are a leading cause of monogenic obesity in humans and cause excessive obesity and hyperphagia in mice." (PMID 40674128, 2025). "Setmelanotide is an FDA-approved agonist of MC4R for adults and children aged 6 years and older diagnosed with monogenic obesity linked to specific unbenign genetic variants of POMC, PCSK1, or LEPR or those with Bardet-Biedl syndrome." (PMID 40104296, 2025). "Fourth, specific loci, such as FTO and MC4R, contain distinct alleles associated with severe obesity or thinness." (PMID 38849463, 2025). "Few cases of monogenic obesity exist, with the most frequently encountered mutation being in the melanocortin 4 receptor (MC4R)." (PMID 41013830, 2025). "Ten identified publications reported effects of setmelanotide on weight, hunger, or health-related QOL (HRQOL) in patients with rare MC4R pathway diseases associated with hyperphagia and obesity." (PMID 40560452, 2025).